IL17RA (interleukin 17 receptor A)
Diseases named in the same sentence as IL17RA in open-access papers (continued):
Sharing a sentence is not in itself a finding about the gene and the disease.
liver fibrosis (8 papers, 2013 to 2024). "Moreover, IL-17RA deficiency largely protected mice from CCl4-induced liver fibrosis and inflammation-induced damage." (PMID 33789737, 2021). "Compared with WT mice, liver fibrosis is decreased in IL-17RA-deficient mice." (PMID 32611373, 2020). "Interestingly, the decrease in hepatic fibrosis was completely mediated by Il17ra deficiency on hematopoietic cells." (PMID 24454873, 2014). "Furthermore, IL-17A and IL-17RA deficiency protects mice from liver fibrosis induced by CCl4 and bile duct ligation." (PMID 24223606, 2013). "Pharmacological or genetic inhibition of IL-17 production or its signaling pathway (Il17a-/- or Il17ra-/- mice, respectively) in various liver fibrosis models led to reduced HSC activation and limited liver fibrosis progression." (PMID 39156888, 2024).
prostate carcinoma (8 papers, 2016 to 2025). A carcinoma that arises from epithelial cells of the prostate gland. "The expression of IL-17A cytokine and its receptor IL-17RA may be used to predict the risk of aggressive prostate cancer." (PMID 37760548, 2023). "Compared with normal cells, IL-17RA phosphorylation in proliferative human prostate cancer cells decreased, while IL-17RA levels increased." (PMID 39906741, 2024). "We found that, in obese mice, hyperinsulinemia enhanced IL-17-induced expression of downstream proinflammatory genes with increased levels of IL-17 receptor A (IL-17RA), resulting in development of more invasive prostate cancer." (PMID 26871944, 2016). "IL-17RA phosphorylation was reduced, while the IL-17RA levels were increased in the proliferative human prostate cancer cells compared to the normal cells." (PMID 26871944, 2016). "In contrast, the levels of IL-17RA are higher in prostate cancer than in the normal prostatic glands, which is consistent to a previous report." (PMID 26871944, 2016). "Concordantly, phosphorylated IL-17RA was decreased, and its IL-17RA mRNA levels were raised in the proliferative human prostate cancer cells compared to the normal cells." (PMID 27589729, 2016).
colorectal cancer (7 papers, 2020 to 2026). A primary or metastatic malignant neoplasm that affects the colon or rectum. "Previous studies have established that IL-17RA plays a role in promoting tumor progression, inflammation, and immune evasion in various cancers, including colorectal cancer." (PMID 41438576, 2026). "Interleukin 17 receptor A (IL-17RA) is a key mediator in colorectal cancer (CRC) pathogenesis and progression." (PMID 41438576, 2026). "This study aimed to investigate the role of IL-17RA in promoting cancer stem-like properties and its impact on colorectal cancer prognosis and chemoresistance." (PMID 41438576, 2026). "Preliminary data indicate that IL-17RA overexpression upregulates IL-17A expression in colorectal cancer cells, suggesting the presence of an autocrine loop that could enhance receptor signaling (Data not shown)." (PMID 41438576, 2026). "Interleukin 17 receptor A (FC = 0, p = 2.50E-02) is the receptor for interleukin-17A, which is a pro-inflammatory cytokine related to the rapid malignant progression and treatment resistance of colorectal cancer." (PMID 40709343, 2025). "In addition, IL17RA deletion predicts high-grade colorectal cancer and poor clinical outcomes." (PMID 37359548, 2023). "Our study provides novel evidence that IL-17RA overexpression directly enhances the expression of CSC markers and sphere-forming capacity in colorectal cancer cells." (PMID 41438576, 2026).
dermatitis (7 papers, 2016 to 2024). An inflammatory process affecting the skin. "A negative TCF4/IL-17C/ TNF-a/ IL-17A feedback loop decreases TCF4 in an IL-17RA/RE-dependent manner and is further amplified by IL-17C/TCF4 regulation of ZC3H12A and IL-17C regulation of NFKBIZ, resulting in self-sustaining skin inflammation." (PMID 38470486, 2024). "Finally, Zc3h12a expression correlated with measures of skin inflammation, such that Zc3h12a increased in KC-Tie2 mice compared with control animals and decreased in the absence of Il17c, Il17re, and Il17ra." (PMID 38470486, 2024). "In addition, while the deletion of IL-17RA in T cells, neutrophils, or macrophages has no impact on IMQ-induced dermatitis, only deletion of this receptor in keratinocytes reflects the effects of its systemic deletion, resulting in strongly reduced dermatitis development." (PMID 32752186, 2020).
Immunodeficiency (7 papers, 2017 to 2024). Failure of the immune system to protect the body adequately from infection, due to the absence or insufficiency of some component process or substance. "Therefore, we suspect that the mutation in the IL-17RA gene possibly collaborated with his immunodeficiency and led to the urinary tract infection." (PMID 36814216, 2023). "It is considered to be a T cell-dependent immune disease whose pathogenesis is influenced by cytokines, such as IL-10, IL-17A, IL-17RA, IL-23A and IL-23R." (PMID 34945130, 2021). "In addition, mice with knock out of IL-17RA and RC, which are receptors for IL-17A and F, respectively, are highly sensitive to the immune disease, Graft-vs.-host disease (GVDH)." (PMID 32256492, 2020). "With this consideration, we have noted the presence of rare variants in other immunodeficiency genes (JAK2, JAK3, IL17RA, IL12RB2, CARD14, and TYK2) in our various patients, which could feasibly contribute to the penetrance and/or differences in the clinical phenotypes of the patients." (PMID 36672844, 2022).
Obesity (7 papers, 2016 to 2024). Accumulation of substantial excess body fat. "Additionally, murine non-alcoholic fatty liver disease (NAFLD) model and murine chronic liver injury model were utilized to investigate the role of IL-17RA regulated by m6A mRNA modulator fat mass and obesity-associated (FTO) in chronic hepatic inflammation." (PMID 36172147, 2022). "Increased level of insulin in obesity stabilized human IL17RA via decreasing the phosphorylation at T780." (PMID 36009523, 2022). "Notably, IL-17RA signaling, via IL-17A, plays an important role in obesity-driven NAFLD pathogenesis." (PMID 26895034, 2016). "By using IL-17RA−/−mice, the authors of one study reported that IL-17RA signaling regulated liver injury in the progression of NAFLD; the neutralization of IL-17A, meanwhile, significantly reduced obesity-driven hepatocellular damage." (PMID 39000005, 2024). "Down-regulation of IL17RA, a downstream gene of ZNF574 (the hub gene in the pink module), was found to reduce the side effects of obesity in mice fed with high energy diet for 9 weeks." (PMID 36439361, 2022). "While IL-17RA, in part via IL-17A, was previously determined to regulate obesity-dependent NAFLD, our novel data show that hepatic IL-17RA expression is actually increased during MCDD-induced NAFLD." (PMID 26895034, 2016). "Given that: (a) IL-17A has a causal role in multiple models of liver injury; (b) IL-17F shares a receptor with IL-17A; and (c) IL-17RA mice are protected from obesity-induced NASH, we hypothesized that both IL-17A and IL-17F signaling through IL-17RA is critical to NAFLD progression." (PMID 26895034, 2016).
pancreatic cancer (7 papers, 2020 to 2026). "Chandra and colleagues embarked on a study to explore the impact of extra‐tumoral IL‐17A/IL‐17RA signaling on the growth of pancreatic tumors, leading to the observation of unexpected outcomes associated with IL‐17RA deficiency." (PMID 38585232, 2024). "The pivotal finding of the study elucidated that extra‐tumoral IL‐17RA deficiency or blockade unexpectedly elicited the secretion of IL‐17A in response to microbial stimuli, subsequently leading to the systemic elevation of IL‐17A levels and promoting the growth of pancreatic tumors." (PMID 38585232, 2024). "Recent research has revealed the existence of a non-canonical CD8+ T-cell subpopulation that produces IL-17A, which can promote pancreatic cancer progression through IL-17RA signaling." (PMID 37686343, 2023). "To investigate the IL-17A/IL-17RA axis in pancreatic cancer, we inhibited IL-17A signaling in a murine model of pancreatic cancer." (PMID 32210079, 2020). "It is unclear whether this observation is also valid for pancreatic cancer, and whether IL-17A/IL-17RA neutralization is a promising therapy for PDAC." (PMID 32210079, 2020). "We have asked whether the IL-17A/IL-17RA axis promotes the aggressiveness of pancreatic cancer." (PMID 32210079, 2020). "Our current in vitro and in vivo data could not show an association between IL-17A/IL-17RA signaling and the aggressiveness of pancreatic cancer." (PMID 32210079, 2020). "We retrieved IL-17RA and IL17A gene expression levels from publicly available transcriptomic data of 903 patients with pancreatic cancer." (PMID 32210079, 2020). "Together, these results suggest that IL-17A/IL-17RA expression does not affect the survival of pancreatic cancer patients." (PMID 32210079, 2020). "Blocking the IL-17A/IL-17RA axis in a murine pancreatic cancer model did not improve the survival of mice, but reduced the tumor burden slightly." (PMID 32210079, 2020). "While we have shown IL-17RA expression in both human and murine pancreatic cancer cells, IL-17A does not increase “aggressiveness” of pancreatic cancer cell lines in terms of inducing cancer stem cell features." (PMID 32210079, 2020). "Blocking IL-17A/IL-17RA signaling does not interfere with pancreatic cancer development and progression and may not be considered as a promising monotherapy for PDAC." (PMID 32210079, 2020).
periodontitis (7 papers, 2017 to 2026). An acute or chronic inflammatory process that affects the tissues that surround and support the teeth. "Another study indicates a reverse relationship between IL-23R and IL-17RA in chronic and aggressive periodontitis patients, potentially linked to RANKL activation and alveolar bone loss." (PMID 39659491, 2024). "Most of these studies, including our working group, demonstrate an increase in IL‐23, IL‐17A, and IL‐17RA in GT from patients with periodontitis." (PMID 41536464, 2026). "We observed a significant increase in IL‐17RA protein expression in the periodontitis group versus the control group." (PMID 41536464, 2026). "Meanwhile, in the group of patients with periodontitis, significant correlations were found between: IL‐23R and IL‐23 [r = 0.469 (p = 0.021)]; as well as between IL‐17RA and IL‐17A [r = 0.713(p < 0.001)] and with IL‐23 [r = 0.637 (p = 0.001)]." (PMID 41536464, 2026). "There is a tendency toward increased IL‐23, IL‐17, and IL‐17 receptor (IL‐17RA) and a discrepancy in IL‐23 receptor (IL‐23R) in gingival tissue (GT) of patients with periodontitis." (PMID 41536464, 2026). "At protein level, we demonstrated an increase in IL‐17RA and, conversely, a decrease in IL‐23R in GT from patients with periodontitis compared to healthy subjects using the ELISA technique." (PMID 41536464, 2026). "We found a significant increase in IL‐23, IL‐17A, IL‐23R, and IL‐17RA protein levels in the periodontitis group compared with the healthy group; we also detected bands with unexpected molecular weights for both receptors." (PMID 41536464, 2026). "Likewise, IL‐17RA (120 kDa) expression was significantly higher in subjects with periodontitis (median 0.804, IQR 0.895) compared with healthy subjects (median 0.479, IQR 0.389; p = 0.004)." (PMID 41536464, 2026). "An analysis of N‐glycan removal, LC/MS/MS, and peptide mapping could help elucidate whether these bands are immature proteins or isoforms of IL‐23R and IL‐17RA in periodontitis." (PMID 41536464, 2026). "Thus, IL‐17RA overexpression in GT of patients with periodontitis might correspond to the receptor expressed on the fibroblast membrane and receptors at the intracellular level." (PMID 41536464, 2026).
glioma (6 papers, 2016 to 2025). A benign or malignant brain and spinal cord tumor that arises from glial cells (astrocytes, oligodendrocytes, ependymal cells). "Building on the unexpected outcomes of global IL‐17RA deficiency, Chandra and colleagues then explored the systemic impact of disrupted IL‐17A/IL‐17RA signaling in the intestine, focusing on both pancreatic and syngeneic murine glioma (GBM) tumors." (PMID 38585232, 2024). "Their investigation delved into the systemic ramifications of disrupted IL‐17A/IL‐17RA signaling in the intestine, targeting both pancreatic and syngeneic murine glioma (GBM) tumors." (PMID 38585232, 2024). "Furthermore, IL‐17RA involved in cell‐renewal of glioma cells." (PMID 38491831, 2024). "We have observed, for the first time, preferential co-localization of IL-17RA (referred to as IL-17R in this manuscript) with GSC markers in human primary malignant gliomas, suggesting that IL-17R+ glioma cells may represent a subpopulation of GSCs." (PMID 26755664, 2016).
Hepatitis (6 papers, 2013 to 2025). Inflammation of the liver. "In contrast, IL-17RA-/-, IL-17A-/- and IL-17F-/- mice fed MCDD primarily displayed centrilobular, macrovesicular hepatic lipidosis with mild to moderate levels of hepatic inflammation based on H&E staining." (PMID 26895034, 2016).
influenza (6 papers, 2010 to 2023). An acute viral infection of the respiratory tract, occurring in isolated cases, in epidemics, or in pandemics; it is caused by serologically different strains of viruses (influenzaviruses) designated A, B, and C, has a 3-day incubation period, and usually lasts for 3 to 10 days. "Paradoxically, the pathologic role of IL-17RA has been previously shown in influenza lung models, as IL-17RA deficient mice had reduced lung pathology and higher survival." (PMID 38060620, 2023). "In this study, we investigated the role of interleukin IL-17 recetor A (IL-17RA) as a modulator of influenza host response and inflammation in the upper respiratory tract." (PMID 38060620, 2023). "The critical role of IL-17 receptor (IL-17RA) signaling has been shown in acute immunopathology of influenza-infected lungs, as IL-17RA knockout mice had reduced tissue damage, reduced neutrophil numbers, and increased survival." (PMID 30333833, 2018). "In one study, IL-17RA knockout mice had improved survival following lethal influenza viral challenge as compared to wild type mice, suggesting a detrimental effect of IL-17 in the course of influenza infection." (PMID 22069479, 2011). "Future investigations are required to determine whether IL-17RA is a common pathologic framework against respiratory viruses other than influenza." (PMID 38060620, 2023). "Using an experimental mouse model with localized nasopharyngeal influenza infection, we show that IL-17RA, a receptor for interleukin IL-17A, is a significant contributor to influenza tissue damage in the nasopharynx and promotes severe bacterial co-infection by Streptococcus pneumoniae." (PMID 38060620, 2023). "Our findings suggest that IL-17RA is a significant pathologic axis that could be utilized as a therapeutic target to treat influenza upper respiratory infections." (PMID 38060620, 2023).
osteosarcoma (6 papers, 2016 to 2026). A usually aggressive malignant bone-forming mesenchymal neoplasm, predominantly affecting adolescents and young adults. "IL-17 can facilitate the susceptibility of osteosarcoma cells to NK cell lysis, and IL-17A/IL-17RA interaction can promote osteosarcoma cells metastasis, indicating that targeting IL-17 may be a novel promising strategy to treat osteosarcoma patients." (PMID 37732314, 2023). "Besides, IL-17A/IL-17RA interaction promoted metastasis of osteosarcoma cells." (PMID 30849987, 2019).
bladder cancer (5 papers, 2016 to 2024). "Here we analyzed the IL-17 family cytokines IL-17A, E and F and their receptors IL-17RA, RB and RC in bladder tissues from patients with cystitis, polyp and bladder cancer." (PMID 27716046, 2016). "We compared expression and location of IL-17 cytokine family IL-17A, IL-17E and IL-17 F and their receptors IL-17RA, IL-17RB and IL-17RC in tissues derived from subjects with cystitis, bladder polyp and bladder cancer in parallel." (PMID 27716046, 2016). "The results of a complex study on the immunoreactivity of the ligands and receptors of the IL-17 family in patients with bladder cancer showed significantly elevated IL-17A, IL-17F, and IL-17RC immunoreactivity in the bladder cancer group but decreased IL-17E, IL-17RA, and IL-17RB immunoreactivity." (PMID 37371647, 2023). "In contrast to IL-17A, global IL-17RA immunoreactivity was significantly elevated in cystitis and polyp compared with those of bladder cancer (p = 0.001 and p = 0.001, respectively), while global IL-17RA immunoreactivity was significantly higher in polyps than those of cystitis (p = 0.015)." (PMID 27716046, 2016). "In the present study, expression of IL-17A and IL-17 F increased but IL-17RA decreased in bladder cancer, suggesting that IL-17A and IL-17 F are possibly expressed by different profiles of cellular populations and mainly through binding IL-17RC to exert biological effects." (PMID 27716046, 2016). "Compared with subjects with cystitis, immunoreactivity for IL-17A, IL-17 F and IL-17RC was significantly elevated in the group of bladder cancer (p < 0.01), while immunoreactivity of IL-17E, IL-17RA and IL-17RB, and the infiltrating neutrophils were decreased (p < 0.05)." (PMID 27716046, 2016). "The purpose of this study was to assess the expression of CXCR2, IL-17RA, and IL-17RC genes at the mRNA level as well as tissue and serum levels of IL-17A, vascular endothelial growth factor (VEGF), and transforming growth factor β (TGF-β) in patients with bladder cancer (BC) compared to control." (PMID 38515019, 2024).
colon tumors (5 papers, 2019 to 2025). "The expression and activation of IL-17RA can directly promote the tumorigenesis of colon cancer cells." (PMID 40452847, 2025). "IL-17A binds to its type A receptor (IL-17RA), with several studies showing that IL-17A and IL-17RA expression is higher in colon tumor than in normal colon tissues." (PMID 35991881, 2022). "Indeed, immunostaining of cryosectioned colonic tumors showed that ablation of IL-17RA resulted in a marked increase in the number of CD8+ T cells in sporadic colorectal tumors." (PMID 31775909, 2019). "Loss of IL-17RA in this model also resulted in marked elevation in the number of CD8+ CTLs in tumors, demonstrating an inhibitory role of IL-17 signaling in limiting CTL infiltration in early stage colon tumors." (PMID 31775909, 2019).
fungal infection (5 papers, 2022 to 2024). "In many models of bacterial or fungal infection, including H. pylori infection, in germline IL-17RA–deficient mice, neutrophil recruitment was impaired." (PMID 38639570, 2024). "Because Il17a transcript levels were elevated in the HNI + OPC condition, we next determined if IL-17/IL-17RA were still protective against fungal infection during this specific form of immunosuppression." (PMID 35628751, 2022). "However, this patient did not carry any variants in CARD9, IL17RA, L17RC, IL17F, STAT1, DOCK8, MALT1, or TRAF3IP2 genes that can explain the susceptibility to a severe and invasive fungal infection." (PMID 35091979, 2022).
lupus (5 papers, 2013 to 2025). "A role for IL-17RA signaling has been shown in disease progression in lupus prone BXD2 mice." (PMID 30858513, 2019).
melanoma (5 papers, 2015 to 2023). A malignant, usually aggressive tumor composed of atypical, neoplastic melanocytes. "Gene expression comparisons between pre- and on-treatment melanoma patient samples showed a significant overall increase in IL17RA, TGFB1, and CCR5 when patients received anti-PD-1." (PMID 33972557, 2021).